USP39 (ubiquitin specific peptidase 39)
Description:
Deubiquitinating enzyme that plays a role in many cellular processes including cellular antiviral response, epithelial morphogenesis, DNA repair or B-cell development. Plays a role in pre-mRNA splicing as a component of the U4/U6-U5 tri-snRNP, one of the building blocks of the precatalytic spliceosome. Specifically regulates immunoglobulin gene rearrangement in a spliceosome-dependent manner, which involves modulating chromatin interactions at the Igh locus and therefore plays an essential role in B-cell development (By similarity). Regulates AURKB mRNA levels, and thereby plays a role in cytokinesis and in the spindle checkpoint. Regulates apoptosis and G2/M cell cycle checkpoint in response to DNA damage by deubiquitinating and stabilizing CHK2. Also plays an important role in DNA repair by controlling the recruitment of XRCC4/LIG4 to DNA double-strand breaks for non-homologous end-joining repair. Participates in antiviral activity by affecting the type I IFN signaling by stabilizing STAT1 and decreasing its 'Lys-6'-linked ubiquitination. Contributes to non-canonical Wnt signaling during epidermal differentiation (By similarity). Acts as a negative regulator NF-kappa-B activation through deubiquitination of 'Lys-48'-linked ubiquitination of NFKBIA.
Synonyms: CGI-21; HSPC332; SAD1; SNRNP65; 65K
Tractability: Small molecule: a structure with a bound ligand is known. PROTAC: UniProt records ubiquitination sites on it; ubiquitination databases record sites on it; its protein half-life has been measured.
Target class: Enzyme; Hydrolase
Gene: Protein-coding gene on chromosome 2 (85,602,856 to 85,657,710, forward strand). Ensembl gene ENSG00000168883.
Subcellular location: Nucleus
Subcellular location (Human Protein Atlas): Nucleoplasm
Pathways (Reactome):
Metabolism of RNA: mRNA Splicing - Major Pathway
Gene Ontology:
Molecular function: cysteine-type deubiquitinase activity; protein binding; zinc ion binding
Biological process: mRNA splicing, via spliceosome; spliceosomal complex assembly; mRNA processing; RNA splicing; spliceosomal snRNP assembly; spliceosomal tri-snRNP complex assembly; spliceosome conformational change to release U4 (or U4atac) and U1 (or U11); protein deubiquitination
Cellular component: nucleoplasm; nucleus; precatalytic spliceosome; spliceosomal complex; U12-type precatalytic spliceosome; U4/U6 x U5 tri-snRNP complex; U4atac/U6atac x U5 tri-snRNP complex
Genetic constraint (gnomAD): Loss-of-function variants: 38 observed, 66.97 expected, observed/expected ratio (o/e) 0.57, 90% interval 0.44 to 0.74. The upper end of that interval is the gene's LOEUF score, 0.74, which puts it in group 3 of 6, group 1 being the genes least tolerant of losing a copy. Missense variants: 608 observed, 723.22 expected, observed/expected ratio (o/e) 0.84, 90% interval 0.79 to 0.9. Synonymous variants: 303 observed, 275.53 expected, observed/expected ratio (o/e) 1.1, 90% interval 1 to 1.21.
Homologues: Orthologues: chimpanzee USP39 (99% identical), rabbit USP39 (98% identical), dog USP39 (98% identical), guinea pig USP39 (98% identical), pig USP39 (97% identical), mouse Usp39 (97% identical), rat Usp39 (97% identical), macaque USP39 (88% identical), tropical clawed frog usp39 (80% identical), zebrafish usp39 (76% identical), Caenorhabditis elegans usp-39 (56% identical), Drosophila melanogaster Usp39 (54% identical). Paralogues in human: USP12 (15% identical), USP46 (15% identical).
Diseases named in the same sentence as USP39 in open-access papers:
USP39 is named in the same sentence as 68 diseases in open-access papers, as found by Europe PMC text mining. Sharing a sentence is not in itself a finding about the gene and the disease. The quoted sentences say what the papers report.
hepatocellular carcinoma (20 papers, 2015 to 2025). A malignant tumor that arises from hepatocytes. "Substantial literature has revealed that USP39 exerts oncogenic impact on the development of various malignancies such as osteosarcoma, hepatocellular carcinoma, and glioma." (PMID 37957720, 2023). "Accumulating evidences prove that USP39 participates in the development of hepatocellular carcinoma (HCC)." (PMID 36707504, 2023). "A previous study suggested that SIRT7 promoted the deacetylation of USP39 in hepatocellular carcinoma cells." (PMID 37957720, 2023). "The role of deubiquitinating enzyme USP39 had been demonstrated in the progression of hepatocellular carcinoma." (PMID 35654790, 2022). "Studies have also shown that USP39 plays a vital role in cancer development, including breast cancer and hepatocellular cancer, where upregulation of USP39 was observed." (PMID 34177595, 2021). "Emerging evidence suggests that USP39 plays an important role in the development of hepatocellular carcinoma (HCC)." (PMID 33649471, 2021). "For example, upregulation of USP39 in hepatocellular carcinoma contributes to the growth of SMMC-7721 cells via regulating the pre-mRNA splicing of FoxM1." (PMID 33255748, 2020). "USP39 regulates the growth of hepatocellular carcinoma cells via regulating the transcriptional factor FoxM1." (PMID 30898977, 2019). "Knockdown of USP39 has been reported to inhibit the growth of hepatocellular carcinoma (HCC), breast cancer and medullary thyroid carcinoma cells." (PMID 26959883, 2016). "In the present study, we investigated the functions of USP39 in human hepatocellular carcinoma (HCC) cell line SMMC-7721." (PMID 25889525, 2015). "Downregulation of USP39 induced a remarkable pro-apoptotic effect in human hepatocellular carcinoma SMMC-7721 cells." (PMID 25889525, 2015). "Additionally, in the study of tumor prognosis, it was found that USP39 was closely related to the prognosis of patients with hepatocellular carcinoma, pancreatic ductal adenocarcinoma, glioma, neuroblastoma and other malignant tumors." (PMID 40672756, 2025). "A large number of studies have found that USP39 is highly expressed in hepatocellular carcinoma tissues and cells, and the aberrant expression of USP39 may significantly contribute to the development of hepatocellular carcinoma." (PMID 40672756, 2025). "Their stabilization by USP39 induces chemo-radiation resistance, promotes tumorigenesis in hepatocellular carcinoma (HCC), sustains IFN-Induced antiviral immunity, facilitates breast cancer cell proliferation, promotes tumor cell proliferation and glioma and HCC progression, respectively." (PMID 39736693, 2024). "USP39 has been reported to positively regulate FOXM1 expression in hepatocellular carcinoma cells." (PMID 37957720, 2023). "USP39 has been reported to positively regulate FOXM1 expression in hepatocellular carcinoma." (PMID 37957720, 2023). "SIRT7 promotes hepatocellular carcinoma development via deacetylation of USP39." (PMID 37957720, 2023). "Moreover, SIRT7 has been demonstrated to deacetylate USP39, increasing the stability, and promoting the oncogenic activity of USP39 in hepatocellular carcinoma development." (PMID 37957720, 2023). "Moreover, USP39 upregulation is identified in the pathogenesis of multiple cancers, including hepatocellular carcinoma, medullary thyroid carcinoma and renal cell carcinoma." (PMID 37957720, 2023). "It further confirmed that knockdown of USP39 could suppress the growth of hepatocellular carcinoma cells through inducing cell apoptosis." (PMID 25889525, 2015). "Furthermore, inhibition of the SUMOylation of USP39 can enhance the proliferation of cancer cells including breast and hepatocellular cancer via affecting the recruitment of tri-snRNP, suggesting that SUMOylation of USP39 has an essential role in cancer therapy." (PMID 34177595, 2021). "Accumulating evidence has shown that USP39 participated in the proliferation and metastasis of hepatocellular carcinoma (HCC)." (PMID 34987596, 2021).
hepatocellular carcinoma (continued). "Additionally, USP39 regulates the growth of hepatocellular carcinoma via Forkhead box M1 (FoxM1)." (PMID 30898977, 2019). "Therefore, we could draw the conclusion that USP39 silencing led to the proliferation inhibition in human hepatocellular carcinoma presumably as a result of the induction of apoptosis." (PMID 25889525, 2015). "Thus, we may conclude that USP39 is involved in signaling pathways that intervene hepatocellular carcinoma cell apoptosis." (PMID 25889525, 2015). "Our results are in perfect agreement with those of Dr. Gang Song's team, who elegantly demonstrated that USP39 and the E3 ligase TRIM26 balance the level of ZEB1 ubiquitination and thereby determine hepatocellular carcinoma cell proliferation and migration." (PMID 39736693, 2024). "USP39 and E3 ligase TRIM26 balance the level of ZEB1 ubiquitination, thereby determining the progression of hepatocellular carcinoma." (PMID 36906615, 2023). "Our previous studies showed that the deubiquitination enzyme USP39 and the E3 ubiquitin ligase TRIM26 balance the ubiquitination level of ZEB1, thereby determining the progression of hepatocellular carcinoma." (PMID 36707504, 2023). "However, little is known about the mechanism especially deubiquitinating target of USP39 in regulating hepatocellular carcinoma (HCC) growth." (PMID 36707504, 2023). "Mechanistically, TRIM26 ubiquitinates and targets ZEB1 for degradation, while USP39 deubiquitinates and stabilizes ZEB1 to promote hepatocellular carcinoma (HCC)." (PMID 35454770, 2022). "Mechanistic studies suggest that USP39 stabilizes ZEB1 protein through deubiquitination and activates the development of the EMT pathway and the proliferation and migration of hepatoma cells." (PMID 35875077, 2022). "In the development of hepatoma cells, SIRT7 can deacetylate USP39, which improves the stability of USP39 and promotes the proliferation of HCC." (PMID 35875077, 2022). "Moreover, USP39 and TRIM26 balanced the expression of ZEB1 to regulate proliferation and metastasis of hepatocellular carcinoma." (PMID 36582601, 2022). "Overall, DNAAF5 serves as a scaffold protein to recruit USP39 to form a ternary complex by directly binding the PFKL protein, thereby improving the stability of the latter, which promotes the malignant process of hepatocellular carcinoma." (PMID 36276075, 2022). "Furthermore, existing studies have only explored the role of USP39 in regulating tumor-related signaling pathways, including PI3K/AKT/HIF-1α and Wnt/β-catenin, across a limited range of cancers, such as hepatocellular carcinoma, endometrial cancer, and ovarian cancer." (PMID 40672756, 2025). "It was reported that USP39 upregualtion was correlated with the development of medullary thyroid carcinoma (MTC) and human hepatocellular carcinoma (HCC)." (PMID 34544400, 2021). "However, there is no report about the functions of USP39 in human hepatocellular carcinoma." (PMID 25889525, 2015).
breast carcinoma (12 papers, 2015 to 2025). "The results of our study indicated that USP39 is highly expressed in breast cancer and is associated with a poor prognosis." (PMID 39781342, 2025). "For instance, in HCC, cervical squamous cell carcinoma, and breast cancer, USP39 and FoxM1 exhibit a synergistic effect in driving malignant tumor progression." (PMID 40672756, 2025). "In conclusion, the function of USP39 in influencing the progression of malignant tumors by regulating the expression of various molecules makes it a promising potential target for breast cancer therapy." (PMID 40672756, 2025). "Immunohistochemical staining analysis revealed that USP39 expression was elevated in breast cancer cells." (PMID 40672756, 2025). "Specifically, USP39 promotes breast cancer cell proliferation and tumor growth by deubiquitinating and stabilizing the transcription factor FOXM1." (PMID 39695108, 2024). "Other studies have also reported that USP39 serves as the pro-tumor factor in many malignant tumors such as gastric cancer, osteosarcoma, lung cancer, glioma, and breast cancer." (PMID 34544400, 2021). "Our studies indicate a defect of cell growth and colony formation of HCC cells after knock-down of USP39, which is similar to previous reports of USP39 in breast cancer cells." (PMID 25889525, 2015). "Notably, the regulation of FoxM1 expression by USP39 has only been confirmed in cell lines of triple-negative and estrogen receptor (ER)-positive breast cancer subtypes." (PMID 40672756, 2025). "The expression level of the USP39 protein is elevated in human breast cancer tissues." (PMID 40990019, 2025). "Recently, scientists reported aberrant USP39 expression could inhibit breast cancer cell growth in vitro, however, little is known about how USP39 functions in human osteosarcoma and whether it can be used as an potential therapeutic target." (PMID 28403900, 2017). "Previous studies showed that USP39 is related with tumorigenesis of human breast cancer cells." (PMID 25889525, 2015). "Previous studies found that down-regulation of USP39 could inhibit cell growth and colony formation of human breast cancer cells." (PMID 25889525, 2015). "Our results were consistent with a previous research showing that knockdown of USP39 markedly reduces the proliferation of MCF-7 breast cancer cells, suggesting that USP39 may play a role in cancer development." (PMID 26303214, 2015). "In the USP39 knockdown MCF-7 cell line, breast cancer cell proliferation was inhibited, and the cell cycle transition from G0 to G1 was blocked." (PMID 40672756, 2025). "Lentiviral infection of breast cancer MCF-7 cells with USP39 shRNA induced G0/G1-phase arrest and apoptosis in vitro; the deubiquitinating enzyme USP39 plays important roles in mRNA processing." (PMID 30257488, 2018). "While some of these spliceosome genes, such as SNRPA1, SNRPD1, USP39, HNRNPU, and HNRNPC, have been shown to play an important role in promoting TNBC cell survival, proliferation, and response to chemotherapy, others are yet to be studied in breast cancer." (PMID 39418101, 2024). "USP39 and FOXM1 form a negative feedback loop that co-controls breast cancer cell proliferation." (PMID 40990019, 2025).
lung carcinoma (12 papers, 2020 to 2025). "Finally, using publicly available datasets, significant up-regulation of both KRAS and USP39 was found in lung cancer patients where high expression levels of USP39 were also associated with short survival." (PMID 34065438, 2021). "Knockdown of USP39 significantly reduces the proliferation and colony-forming ability of lung cancer cell lines 95D and A549, leading to cell cycle arrest in the G2/M phase and inducing apoptosis." (PMID 40990019, 2025). "In human lung cancer tissues, the expression of USP39 is typically higher than that observed in normal tissues." (PMID 40990019, 2025). "USP39 was aberrantly expressed in tissues and cells of several lung cancer types compared to normal lung tissue." (PMID 40672756, 2025). "While USP39 is largely identified to participate in alternative splicing, the precise role of USP9x in different types of cancer, in particular lung cancer, is less studied." (PMID 39075050, 2024). "For example, in multiple lung cancer cell lines, downregulation of USP39 confers cancer cells resistance to chemo- and radiotherapy and, conversely, silencing of USP39 in the case of pancreatic cancer induces apoptosis and suppresses tumor growth." (PMID 36732501, 2023). "Recently, studies have shown that USP39 is differentially expressed in lung cancer cells and is related to the development and progression of lung cancer cells and can promote the occurrence and development of tumor cells." (PMID 36046375, 2022). "USP39 has been less studied in lung cancer, but there are studies showing that USP39 was upregulated in lung adenocarcinoma cells and promoted the growth of lung adenocarcinoma cells." (PMID 36046375, 2022). "In this experiment, quantitative real-time PCR (qRT-PCR), western blot, and other methods were used to detect the expression of miR-381 and ubiquitin-specific protease 39 (USP39) in lung cancer tissues." (PMID 36046375, 2022). "Recently, a report showed that USP39 has a deubiquitination-related function towards CHK2 in lung cancer." (PMID 33649471, 2021). "To analyze USP39 expression in lung cancer tissues, using immunohistochemistry we first determined the levels of expression of the USP39 protein in 80 samples from lung cancer patients (comprising 3 normal tissues and 77 lung cancer tissues)." (PMID 33255748, 2020). "Together, these data demonstrate that USP39 knockdown inhibits the metastasis of lung cancer cells in vivo and in vitro." (PMID 33255748, 2020). "To investigate the roles of USP39 in lung cancer, we generated USP39 shRNAs (control, S1 and S2) lentiviruses and established A549 and HCC827 cell lines stably expressing these shRNAs." (PMID 33255748, 2020). "In the present study, we examined the expression of USP39 in lung cancer and found that it was significantly upregulated in lung cancer tissues compared with normal lung tissues." (PMID 33255748, 2020). "Here, we reported that USP39 is frequently overexpressed in human lung cancer tissues and non-small-cell lung cancer (NSCLC) cell lines." (PMID 33255748, 2020). "Additionally, USP39 deubiquitinates and stabilizes CHK2 in lung cancer, and the knockdown of USP39 compromises G2/M checkpoint, thereby conferring decreased apoptosis and resistance to chemotherapy and radiotherapy." (PMID 36694209, 2023). "Next, we examined the expression of USP39 in lung cancer cells." (PMID 36046375, 2022).